DHDDS (dehydrodolichyl diphosphate synthase subunit)
Description:
With NUS1, forms the dehydrodolichyl diphosphate synthase (DDS) complex, an essential component of the dolichol monophosphate (Dol-P) biosynthetic machinery. Both subunits contribute to enzymatic activity, i.e. condensation of multiple copies of isopentenyl pyrophosphate (IPP) to farnesyl pyrophosphate (FPP) to produce dehydrodolichyl diphosphate (Dedol-PP), a precursor of dolichol phosphate which is utilized as a sugar carrier in protein glycosylation in the endoplasmic reticulum (ER). Synthesizes long-chain polyprenols, mostly of C95 and C100 chain length. Regulates the glycosylation and stability of nascent NPC2, thereby promoting trafficking of LDL-derived cholesterol.
Synonyms: CIT; HDS; FLJ13102; DS; RP59; hCIT; CPT; DEDSM
Tractability: Small molecule: a structure with a bound ligand is known. Antibody: UniProt places it where antibodies can reach, with high confidence. PROTAC: ubiquitination databases record sites on it; its protein half-life has been measured.
Gene: Protein-coding gene on chromosome 1 (26,432,282 to 26,471,322, forward strand). Ensembl gene ENSG00000117682.
Subcellular location: Endoplasmic reticulum membrane
Subcellular location (Human Protein Atlas): Plasma membrane
Pathways (Reactome):
Disease: Defective DHDDS causes RP59
Metabolism of proteins: Synthesis of dolichyl-phosphate
Gene Ontology:
Molecular function: ditrans,polycis-polyprenyl diphosphate synthase [(2E,6E)-farnesyl diphosphate specific] activity; prenyltransferase activity; protein binding; transferase activity, transferring alkyl or aryl (other than methyl) groups
Biological process: dolichyl diphosphate biosynthetic process; dolichyl monophosphate biosynthetic process; polyprenol biosynthetic process
Cellular component: dehydrodolichyl diphosphate synthase complex; endoplasmic reticulum membrane
Genetic constraint (gnomAD): Loss-of-function variants: 16 observed, 45.35 expected, observed/expected ratio (o/e) 0.35, 90% interval 0.24 to 0.54. The upper end of that interval is the gene's LOEUF score, 0.54, which puts it in group 2 of 6, group 1 being the genes least tolerant of losing a copy. Missense variants: 338 observed, 440.29 expected, observed/expected ratio (o/e) 0.77, 90% interval 0.7 to 0.84. Synonymous variants: 149 observed, 171.74 expected, observed/expected ratio (o/e) 0.87, 90% interval 0.76 to 0.99.
Gene-disease validity (ClinGen):
ClinGen rates the evidence that DHDDS causes each of these diseases.
DHDDS-CDG (autosomal recessive): Definitive. Any congenital disorder of glycosylation caused by variants in the DHDDS gene.
Homologues: Orthologues: macaque DHDDS (99% identical), chimpanzee DHDDS (99% identical), pig DHDDS (96% identical), guinea pig DHDDS (93% identical), mouse Dhdds (92% identical), rat Dhdds (92% identical), rabbit DHDDS (87% identical), dog DHDDS (78% identical), tropical clawed frog dhdds (71% identical), zebrafish dhdds (69% identical), Drosophila melanogaster Dhdds (45% identical), Caenorhabditis elegans T01G1.4 (36% identical).
Diseases named in the same sentence as DHDDS in open-access papers:
DHDDS is named in the same sentence as 22 diseases in open-access papers, as found by Europe PMC text mining. Sharing a sentence is not in itself a finding about the gene and the disease. The quoted sentences say what the papers report.
retinitis pigmentosa (4 papers, 2014 to 2022). Retinitis pigmentosa (RP) is an inherited retinal dystrophy leading to progressive loss of the photoreceptors and retinal pigment epithelium and resulting in blindness usually after several decades. "Retinitis pigmentosa-59 (RP59) is a rare, recessive form of RP, caused by mutations in the gene encoding DHDDS (dehydrodolichyl diphosphate synthase)." (PMID 36362109, 2022). "The clinical phenotype of the patient reported here resembles that of other CDG-I patients and contrasts with the retinitis pigmentosa phenotype of the first reported DHDDS-deficient patients." (PMID 27343064, 2016). "The functional homolog of Rer2, DHDDS (or hCIT), has been linked to retinitis pigmentosa." (PMID 24868093, 2014). "Patients with certain defects in the dehydrodolichyl diphosphate synthase (DHDDS) gene (RP59; OMIM #613861) exhibit classic symptoms of retinitis pigmentosa, as well as macular changes, suggestive of retinal pigment epithelium (RPE) involvement." (PMID 32245241, 2020).
retinal disease (2 papers, 2020 to 2021). "While, in principle, it would be reasonable to consider RP59 as a CDG, due to the associated mutation(s) in DHDDS, there is no direct evidence to demonstrate a glycosylation defect in the human retinal disease or in any animal model of RP59 generated to date." (PMID 32272552, 2020). "Here we investigated the role of Drosophila DHDDS enzyme in the fly retina, using RNAi-mediated knockdown, in order to identify cellular and molecular mechanisms, which might be involved in this retinal disease." (PMID 34290587, 2021).
retinitis pigmentosa 59 (2 papers, 2022 to 2024). Any retinitis pigmentosa in which the cause of the disease is a mutation in the DHDDS gene. "A single missense mutation (K42E) in the gene encoding the enzyme dehydrodolichyl diphosphate synthase (DHDDS), which is required for protein N-glycosylation in all cells and tissues, causes DHDDS-IRD (retinitis pigmentosa type 59 (RP59; OMIM #613861))." (PMID 38256083, 2024).
Leber congenital amaurosis (1 paper, 2025). Leber congenital amaurosis (LCA) is a retinal dystrophy defined by blindness and responses to electrophysiological stimulation (Ganzfeld electroretinogram (ERG)) below threshold, associated with severe visual impairment within the first year of life. "This study only included patients with rod-cone dystrophies or Leber congenital amaurosis (LCA) harboring specific culprit genes (DHDDS, CRB1, and CEP290) and at least 8 eyes that with BCVA measuring better or equivalent to 6/38." (PMID 40455038, 2025).
neurological diseases (1 paper, 2023). "Cis-prenyltransferase is a heterotetramer formed from two DHDDS-NgBR heterodimers, mutations to which have been identified as causing neurological diseases." (PMID 37470039, 2023).
DHDDS also shares sentences with these, for which no sentence is quoted: congenital disorder of glycosylation (2 papers); ovarian carcinoma (2); Ataxia (1); autosomal recessive disease (1); breast carcinoma (1); cancer (1); cervical cancer (1); developmental delay (1); Dystonia (1); epilepsy (1); melanoma (1); metastatic melanoma (1); Myoclonus (1); Renal cyst (1); rod-cone dystrophies (1); Tremor (1); unspecified (1).